CRP (C-reactive protein)
Diseases named in the same sentence as CRP in open-access papers (continued):
Sharing a sentence is not in itself a finding about the gene and the disease.
type 2 diabetes (continued). "In type 2 diabetic patients, sitagliptin treatment reduced the molecular markers of inflammation as CRP and IL-6 in mononuclear cells, as well as circulating levels of TNF-α, IL-1β, IL-6, intracellular adhesion molecules and CRP." (PMID 32848769, 2020). "Diseases such as Parkinson’s disease and type II diabetes did not affect CRP expression (1.83 and 1.84 ng/mL, respectively)." (PMID 32019214, 2020). "COX proportional hazards regression analysis confirmed that MT-COI and STRN, but not COX10, were independently related to time to new event adjusting for age, gender, (ex)-smoking, BMI, blood pressure, type-2 diabetes, HDL- and LDL-cholesterol, triglycerides and hs-C-reactive protein." (PMID 31821324, 2019). "Similarly, here, we showed that higher serum LPS levels were also related to higher hs‐CRP levels (a well‐characterized, standardized biomarker of systemic inflammation), higher HOMA‐IR levels and higher prevalence of type 2 diabetes." (PMID 30950561, 2019). "In the current study, where all women had a history of GDM, those who developed IGT or type 2 diabetes had higher CRP levels, but TNFα, TNFR1, IL-6, and SAA were not significantly different between groups." (PMID 29951553, 2018). "Plasminogen activator inhibitor-1 (PAI-1) but not fibrinogen and CRP were found to predict type 2 diabetes in the Insulin Resistance Atherosclerosis Study, IRAS." (PMID 27581604, 2016). "Furthermore, various longitudinal studies have shown that elevated levels of CRP, IL-1β, IL-6, and TNF-α predict the development of type 2 diabetes." (PMID 27034691, 2016). "Porridge made with Scoparia dulcis leaf extract reduce fasting blood glucose and HbA1c levels without elevating liver enzymes, creatinine, urea and CRP in type 2 diabetic patients." (PMID 26582144, 2015). "Strengths of our study are the large number of patients with type 2 diabetes and a relatively long follow-up time (almost 4 years), with no constraints on CRP levels at baseline." (PMID 25899452, 2015). "In this study we found that CRP was not an important predictor of CVD in patients with type 2 diabetes." (PMID 25899452, 2015). "Chronic administration of sildenafil in diabetic type II (T2DM) patients reduces levels of endothelin, C-reactive protein, interleukin-6, intercellular adhesion molecules (ICAM), and vascular adhesion molecules (VCAM), as well as reducing nitrate/nitrite levels." (PMID 26770022, 2015). "Higher level of RAGE and CRP, HA or use of HA drugs, previous CVD, older age and less years of formal education are the factors increasing the likelihood of having MCI in elderly patients with type 2 diabetes." (PMID 26578953, 2015). "After adjusting for the potential confounding factors, current smokers with type 2 diabetes had significantly higher serum levels of CRP than smokers without type 2 diabetes." (PMID 25105149, 2014). "C-reactive protein levels were not affected by n-3 supplementation (3 g/day for eight weeks) in a randomized control trial for persons with type 2 diabetes; yet IL-2 and TNF-α, other indicators of inflammation, were reduced in the n-3 group." (PMID 31667003, 2013). "No significant changes in CRP were found after two-month supplementation with n-3 for individuals with type 2 diabetes; however, HCY levels were significantly reduced." (PMID 31667003, 2013). "Evidence for the reduction of CRP by n-3 in populations with type 2 diabetes has not been established." (PMID 31667003, 2013). "There are also reports in the literature on patients with type 2 diabetes that found no clear effect of periodontal treatment on CRP and same results can be found in healthy patients with periodontal disease." (PMID 22322513, 2012). "Studies of type 2 diabetes, in the absence of HIV infection, have observed associations between inflammatory markers such as IL-6 and CRP and degree of albuminuria." (PMID 21931772, 2011).
type 2 diabetes (continued). "CRP was significantly higher in participants with BMI ≥ 30 compared with BMI < 30, in those with versus those without type 2 diabetes, and in those who reported versus those who did not report heart disease." (PMID 20123638, 2010). "The study included 520 Chinese patients diagnosed with type 2 diabetes with CRP levels not exceeding 10 mg/L." (PMID 21167068, 2010). "Low-grade chronicinflammation is characterized by increased systemic levels of some cytokinesand C-reactive protein (CRP) and a number of studies have confirmed anassociation between low-grade systemic inflammation on one hand andatherosclerosis and type 2 diabetes on the other." (PMID 19148295, 2008). "Of interest, inflammatory markers (C-reactive protein (CRP) and Interleukin-6 (IL-6)) and glucagon-like peptide-1 (GLP-1) levels were similarly elevated across all subtypes compared to controls, indicating common aspects in Type 2 diabetes molecular pathology despite different clinical phenotypes." (PMID 40022072, 2025). "A few studies have hitherto reported an association between elevated hs-CRP and cardiovascular events in patients with type 2 diabetes, however, the predictive value of hs-CRP for TVD patients with or without type 2 diabetes remains unknown." (PMID 37081535, 2023). "However, in another study, IL18, but not CRP or IL 6, was higher in patients with type 2 diabetes and cardiac autonomic neuropathy." (PMID 35329958, 2022). "This novel biomarker has been shown in multiple cohorts of older individuals to predict the future development of both type 2 diabetes and CVD independently of CRP,15, 16 suggesting that it may capture different upstream inflammatory pathways relevant to both diseases." (PMID 35156387, 2022). "Periodontitis is recognized as a promoter of chronic low-grade systemic inflammatory reaction, defined by increased levels of circulating C-reactive protein (CRP), which may support the development of cardiovascular disease, type 2 diabetes, and other relevant pathologies." (PMID 35887937, 2022). "In patients with Type 2 diabetes mellitus (T2DM) studied using a hyperinsulinemic hypoglycemic clamp, mild hypoglycemia (2.7 mM) induces the production of markers of oxidative stress and inflammation including c-reactive protein and urinary free 8-isoprostoglandin F2α (8-iso PGF2α)." (PMID 33371247, 2020). "Nowadays PCOS is considered a low grade chronic inflammation state, with high serum levels of tumor necrosis factor - α (TNF-α), interleukin-6 and CRP, that could be the link between PCOS and its long-term complications like type 2 diabetes and cardiovascular disease." (PMID 30850700, 2019). "Furthermore, several studies have shown the capacity of statins to reduce CRP levels in patients with acute coronary disease and type II diabetes, despite lack of changes in cholesterol levels." (PMID 30008671, 2018). "This study investigated the relationship between morningness-eveningness and systemic inflammation, as measured by high-sensitivity C-reactive protein (hs-CRP) in 163 non-night shift working patients with abnormal glucose tolerance (86 type 2 diabetes and 77 prediabetes)." (PMID 30367094, 2018). "Patients with type 2 diabetes and those with lower CRP levels were not investigated." (PMID 25899452, 2015). "Current smokers with type 2 diabetes had higher CRP levels than smokers without type 2 diabetes." (PMID 25105149, 2014). "However, previous studies suggested that sugar intake may active inflammation pathways and increase circulatory levels of the inflammatory markers, such as C-reactive protein (CRP) both in health individuals and patients with type 2 diabetes." (PMID 24499591, 2013). "Reduced antioxidant defences in type 2 diabetes result in increased oxidised LDL which promotes increased synthesis of proinflammatory cytokines interleukin-6 (IL-6) and tumour necrosis factor alpha (TNF-α), major and minor modulators, respectively, of blood plasma c-reactive protein (CRP) levels." (PMID 23094144, 2012).
type 2 diabetes (continued). "In individuals without type 2 diabetes, CRP levels of S319 carriers and non-carriers were compared." (PMID 20716378, 2010). "Interestingly, women without type 2 diabetes exhibited greater post-exercise glucose elevations following afternoon high-intensity interval exercise compared with baseline, aligning with the observed higher NT-proBNP and CRP levels during afternoon sessions." (PMID 40580209, 2025). "Furthermore, older adults with type-2 diabetes have shown high hs-CRP levels (data not shown)." (PMID 35570546, 2022). "In type 2 diabetics, a placebo-controlled trial investigating whether a cocoa-rich drink consumed together with a high-fat fast-food style meal might affect CRP, but CRP levels did not change after either intervention, and differences between pre- and post-consumption values could not be observed." (PMID 27240397, 2016). "However, it has not been investigated whether plasma CRP mediates the association between the HNF1A polymorphism and type 2 diabetes." (PMID 20716378, 2010). "Therefore, while HNF1A appears to influence CRP concentrations in the non-diabetic state, chronic elevation of CRP is unlikely mediating the association between the HNF1A polymorphism and the high prevalence of type 2 diabetes in this Aboriginal population." (PMID 20716378, 2010). "In addition, a significant increase in Gram-negative bacteria is also found in type 2 diabetes and CKD patients, which contain LPS in the outer membrane and are associated with the elevation of inflammatory biomarkers such as TNF-α, IL-6, and C-reactive protein (CRP) in fecal microbiota samples." (PMID 37362429, 2023). "Metformin has previously been shown to decrease circulating levels of CRP, IL-6, and TNF-α in patients with type 2 diabetes, however this finding was not replicated in our subjects who were nondiabetic and nonprediabetic." (PMID 37131271, 2023). "Three multivariable analysis models were performed to elevate the independent effects of the hs-CRP and clinical outcomes of TVD patients with or without type 2 diabetes after adjusting for other potential confounders." (PMID 37081535, 2023). "Besides, disease activity index CRP and hs-CRP were also negatively correlated with Metrnl circulation in polycystic ovarian syndrome (PCOS), CAD, impaired glucose tolerance (IGT), GD, and type 2 diabetes Mellitus (T2DM)." (PMID 36911663, 2023). "The purpose of this research is to study the dynamics of C-reactive protein (CRP), IL-6, TNF-α, and interleukin-10 (IL-10) in patients with type 2 diabetes who underwent non-Q-myocardial infarction (non-Q-IM), against the background of ALA." (PMID 32341698, 2020). "The magnitude of the difference observed in CRP levels (11.9%) comparing individuals by median DII scores was greater than that reported between non-cases and cases of type 2 diabetes in the Caerphilly study and CVD events in the Health ABC study." (PMID 30096775, 2018). "Likewise, we hypothesized that the fact that GRSGWAS showed a nonsignificant effect of CRP on celiac disease, ulcerative colitis, rheumatoid arthritis, type 1 diabetes, and type 2 diabetes can be to some extent explained by the significant heterogeneity observed for these outcomes." (PMID 27327646, 2016). "Consistent with this observational data, we previously found that almonds decreased IL-6 and CRP, and TNF-α in Chinese patients with type 2 diabetes but did not affect ICAM-1 or VCAM-1." (PMID 26080804, 2015). "Patients with type 2 diabetes with (p < 0.001) or without LVDD (p = 0.007) had higher serum ST2 levels compared to healthy controls, state found also for hs-CRP levels but not for the corresponding BNP levels (p = 0.213 & p = 0.207 respectively)." (PMID 22104207, 2011). "Moreover, high-sensitivity CRP levels are lower in MODY3 groups than in a non-diabetic group and other diabetic groups, including type 1 and type 2 diabetes, MODY1, MODY2, and MODY5." (PMID 35328643, 2022).
type 2 diabetes (continued). "We have previously reported a higher prevalence of type 2 diabetes among HNF1A S319 carriers compared to non-carriers in this population, which is paradoxical in the context of the current finding of S319 carriers having a low level of CRP." (PMID 20716378, 2010).
myocardial infarction (859 papers, 2006 to 2026). Gross necrosis of the myocardium, as a result of interruption of the blood supply to the area, as in coronary thrombosis. "Anti-inflammatory therapy with canakinumab, or colchicine but not methotrexate has been successful in reducing the risk of CV events in individuals with a previous myocardial infarction, associated with reductions in CRP." (PMID 41308509, 2025). "Elevated levels of CRP have been linked to an increased risk of adverse cardiovascular outcomes, including myocardial infarction (MI), stroke and heart failure." (PMID 41333918, 2025). "CRP’s delayed elevation has raised questions about its role as a diagnostic marker in acute settings, where an early and accurate detection of myocardial infarction is crucial." (PMID 40649166, 2025). "In patients with acute myocardial infarction complicated by cardiogenic shock, higher baseline CRP levels were independently associated with increased 30-day all-cause mortality." (PMID 41552677, 2025). "In 2015, an all-comer PCI registry with the longest follow-up time of 10 years found a significant association of CRP with death and myocardial infarction in patients after first-generation DES implantation." (PMID 41091145, 2025). "Increased CRP levels have been associated with larger infarct size, LV dysfunction, and subsequent adverse clinical outcomes following myocardial infarction." (PMID 40080922, 2025). "One study showed that higher TMAO levels prior to percutaneous coronary angioplasty were independently associated with poorer outcomes in patients with acute myocardial infarction complicated by heart failure, particularly in those with elevated CRP levels." (PMID 40242209, 2025). "Elevated levels of CRP have been implicated in various inflammatory and cardiovascular diseases, particularly acute myocardial infarction (AMI)." (PMID 40649166, 2025). "In 2009, a prospective analysis including a total of 2,691 patients demonstrated an association of CRP with death, myocardial infarction, and ST after early-generation DES implantation and a median follow-up time of 3.9 years." (PMID 41091145, 2025). "After myocardial infarction, elevated CRP levels are associated with adverse cardiac remodeling and an increased risk of heart failure." (PMID 40282303, 2025). "A decline in systemic FAP concentrations was noted acutely after myocardial infarction, with the maximum C-reactive protein level independently being associated with a low FAP concentration." (PMID 40278373, 2025). "Inflammation is a pathogenic paradigm in myocardial infarction, and therefore, C-reactive protein was used." (PMID 41303592, 2025). "In patients with major depressive disorder (MDD), elevated CRP levels are observed in approximately 30–40% of cases and have been associated with a twofold increased risk of myocardial infarction and other adverse cardiovascular events." (PMID 40218134, 2025). "Patients with myocardial infarction with elevated hs-CRP level (≥ 2 mg/L) were at higher risk of major adverse cardiovascular events and death." (PMID 38646625, 2024). "This highlights a synergistic effect of Lp(a) and CRP on cardiovascular risk death in patients with acute myocardial infarction." (PMID 39273236, 2024). "For example, SNPs in the C-reactive protein (CRP) gene increase the risk of myocardial infarction in cardiovascular disease (CVD)." (PMID 38732533, 2024). "The specific treatment for patients with previous myocardial infarction and elevated high-sensitivity CRP with a 150-mg canakinumab dose caused a decrease in recurrent cardiovascular events." (PMID 39274250, 2024). "The level of MMP-9 is directly correlated with the activity of fibrinogen, C-reactive protein, and IL-6, which are markers for predicting the risk of myocardial infarction (MI)." (PMID 39335497, 2024). "Patients in the quartile with the highest CRP values had higher risk of myocardial infarction or stoke compared to those in the lowest quartile." (PMID 38256497, 2024).